NKX2-1 (NK2 homeobox 1)
Diseases named in the same sentence as NKX2-1 in open-access papers (continued):
Sharing a sentence is not in itself a finding about the gene and the disease.
lung adenocarcinoma (continued). "Both pro-tumorigenic and tumor-suppressive roles of NKX2-1 have been reported in lung adenocarcinoma." (PMID 30127261, 2018). "NKX2–1, a key molecule in lung development, is highly expressed in non-small cell lung cancer (NSCLC), particularly in lung adenocarcinoma (ADK), where it is a diagnostic marker." (PMID 29237428, 2017). "The receptor tyrosine kinase-like orphan receptor 1 (ROR1) sustains prosurvival signalling directly downstream of the lineage-survival oncogene NKX2-1/TTF-1 in lung adenocarcinoma." (PMID 26725982, 2016). "In lung adenocarcinomas bearing a NK2 homeobox 1 (NKX2-1) amplification, the oncogenic capacity of LMO3 as a transcription regulator downstream of NKX2-1 has been demonstrated." (PMID 25923053, 2015). "Further, NKX2-1 as a lineage-survival oncogene was reported in T cell acute lymphoblastic leukemia and oncogenic ROR1 and LMO3 directly targeted by NKX2-1 promote lung adenocarcinoma progression." (PMID 25881545, 2015). "For example, NKX2-1 plays lineage-survival oncogene in lung adenocarcinoma and enhanced EFGR-driven lung tumorigenesis." (PMID 25881545, 2015). "This shows an important significance since in human lung adenocarcinoma the expression of Nkx2-1 correlated with a mouse TnonMet gene expression signature." (PMID 22952714, 2012). "NK2-related homeobox transcription factor Nkx2-1 (also called Ttf-1 or Titf1) has been identified as a candidate suppressor of malignant progression in lung adenocarcinoma." (PMID 22952714, 2012). "An overview showing the utilization of unconventional molecular profiling techniques, such as Single‐cell RNA sequencing (scRNA‐seq) and Visium In situ Capturing, employed to unravel the modulatory role of NK2 homeobox 1 (NKX2‐1) within the immune microenvironment of lung adenocarcinoma (LUAD)." (PMID 39113226, 2024). "NKX2-1, a lineage-specific transcription factor, has been noted to be essential for the development of peripheral parts of the lung and in morphogenesis, and it is overexpressed in lung adenocarcinomas." (PMID 37111634, 2023). "Interestingly, some researchers found an opposite phenomenon that NKX2-1 can constrain lung adenocarcinoma in part by repressing the embryonically restricted chromatin regulator Hmga2." (PMID 36203529, 2022). "In lung adenocarcinoma, NKX2-1 has a dual context-dependent tumour-suppressive or -promoting role." (PMID 35954343, 2022). "In contrast, most NKX2-1-positive human lung adenocarcinomas were entirely POU2F3-negative (44/51)." (PMID 33821796, 2021). "Notably, NKX2-1 is not only highly expressed in primary human lung adenocarcinoma, but also its chromosomal locus (14q13.3) is highly amplified in ~10% of human lung adenocarcinomas." (PMID 33980985, 2021). "Finally, we performed IHC for pERK on a panel of mucinous (n = 17, see Materials and methods for inclusion criteria) and NKX2-1-positive primary human lung adenocarcinomas (n = 51)." (PMID 33821796, 2021).
lung adenocarcinoma (continued). "In lung adenocarcinoma, NKX2-1 expression is increased and confers a good prognosis." (PMID 34748583, 2021). "Indeed, in the KrasLSL-G12D GEM model of KRASG12D-driven lung adenocarcinoma, NKX2-1 expression is diminished or silenced in the most poorly differentiated tumors." (PMID 31452510, 2019). "Downregulation of NKX2-1 has been shown to precede dissemination of lung adenocarcinoma cells." (PMID 27874835, 2016). "A large-scale project to characterise copy-number alterations in 371 primary lung adenocarcinomas indicated that amplification of chromosome 14q13.3 is the most common event and NKX2-1 was identified to lie in the minimal 14q13.3 as a novel candidate proto-oncogene." (PMID 25881545, 2015). "NKX2-1 plays a dual role in lung adenocarcinoma progression, but the underling mechanism is not fully understood." (PMID 25881545, 2015). "Furthermore, NKX2-1 enhances together with FOXA1 survival in lung adenocarcinoma by transcriptional activation of LMO3." (PMID 23637834, 2013). "In tumors, variable levels of NKX2-1 expression are detected in 40–50% of non-small cell lung carcinomas (NSCLCs), being higher in lung adenocarcinomas than in squamous cell carcinomas, suggesting that levels of NKX2-1 expression are linked to tumor cell phenotypes." (PMID 22242187, 2012). "Additionally, FOXA2 and CDX2 cooperate with NKX2-1 to inhibit metastasis in lung adenocarcinoma." (PMID 36289750, 2022). "Furthermore, NKX2-1 has been observed to downregulate IKKβ in lung adenocarcinoma." (PMID 35954343, 2022). "So, we tested whether NKX2-1 mediated the specific expression of DSCAM-AS1 in lung adenocarcinoma." (PMID 32929382, 2020). "Moreover, genome-wide chromatin occupancy analysis using lung adenocarcinoma cells has revealed that NKX2-1 colocalizes with Smad3 to regulate a subset of genes while competing with Smad3-Smad4 complex formation resulting in altered genomic binding profiles of Smad3." (PMID 30127261, 2018). "NKX2‐1 fortifies cell–cell junction by upregulating proteins such as E‐Cadherin and repressing EMT, thereby modulating lung adenocarcinoma cell behavior in conjunction with TGFβ." (PMID 39083441, 2025). "NKX2-1/ERK drived Wnt pathway to promote cell proliferation, shorten the value-added cycle, and increased the malignancy of lung adenocarcinoma." (PMID 36703749, 2022). "The ChIP-seq data indicate that NKX2-1 binds to three distinct regions (ATAC inaccessible) at the second intron of LMO3, a product of which is involved in the survival of lung adenocarcinoma cells." (PMID 33980985, 2021). "NK2 homeobox 1, also known as thyroid TF-1 (TTF-1), was demonstrated to be frequently suppressed in high-grade lung adenocarcinoma." (PMID 33931584, 2021).
lung adenocarcinoma (continued). "The lung lineage master regulator gene, Thyroid Transcription Factor-1 (TTF-1, also known as NKX2-1), is used as a marker by pathologists to identify lung adenocarcinomas since TTF-1 is expressed in 60 ~ 70% of lung ADs." (PMID 31142791, 2019). "In lung adenocarcinoma, the developmental transcription factors FOXA2 and Cdx2 function cooperatively with Nkx2-1 as an important regulator in inhibiting metastasis." (PMID 31007610, 2019). "NKX2-1 and TGF-β signaling therefore appear to be a key component for regulating lung adenocarcinoma cell features." (PMID 30127261, 2018). "The potential biomarker, NKX2-1, binds DNA damage-binding protein 1 (DDB1) and degrades check-point kinase 1 (CHK1) to facilitate lung adenocarcinoma progression." (PMID 29069744, 2017). "Lung adenocarcinoma cells were in general strongly positive for NKX2-1 but negative for the thyroid-specific transcription factor PAX8, which is consistent with histopathological features of NSCLC." (PMID 37534159, 2023). "Although organoid-derived subcutaneous tumors do not perfectly mimic the autochthonous BPN model, these data provide additional orthogonal evidence that Cyclin D2 plays a role in the response of NKX2-1-negative lung adenocarcinoma to MAPK inhibition." (PMID 33821796, 2021). "The ChIP-seq data indicate that NKX2-1 binds to five regions (far distal, distal and proximal upstream, and third and sixth introns) of the locus of MYBPH, a product of which is involved in cell motility and metastasis of lung adenocarcinoma." (PMID 33980985, 2021). "To address this question directly, we used conditional alleles of Foxa1 and Foxa2 to abrogate their function in an autochthonous mouse model of NKX2-1-negative lung adenocarcinoma." (PMID 30475207, 2018). "Here, we show that FoxA1 and FoxA2 are required for lung adenocarcinomas to adopt a mucinous, gastric differentiation state in the absence of NKX2-1." (PMID 30475207, 2018). "We show that FoxA1 and FoxA2 regulate the growth and gastric identity of NKX2-1-negative lung adenocarcinoma." (PMID 30475207, 2018). "For example, pancreatic ductal adenocarcinoma (PDAC) and its precursors often express many of the same foregut markers as NKX2-1-negative lung adenocarcinoma." (PMID 30475207, 2018). "Here, we show that the transcription factors FoxA1 and FoxA2 are required for initiation of mucinous NKX2-1-negative lung adenocarcinomas in the mouse and for activation of their gastric differentiation program." (PMID 30475207, 2018). "Taken together, these data show that lack of FoxA1/2 activity at tumor initiation severely impairs the proliferation and long-term growth potential of NKX2-1-negative lung adenocarcinoma." (PMID 30475207, 2018). "In lung adenocarcinoma cell lines NCI-H1975 and SK-LC-5, NKX2-1, a homeodomain transcription factor, has been shown to directly induce the expression of ROR1, which in turn sustains a favorable balance between prosurvival PI3K-AKT and pro-apoptotic p38 signaling." (PMID 28427197, 2017). "In lung adenocarcinoma, NKX2-1 (TITF1) has been shown to drive ROR1 expression and the subsequent increase in ROR1 has two distinct proposed functions, including the potentiation of EGF ligand-induced EGFR signaling and the phosphorylation and activation of c-Src regardless of ligand induction." (PMID 24752542, 2014). "Intriguingly, while even haploinsufficiency of NKX2-1 promoted the appearance of mucinous adenocarcinoma in the KrasLSL-G12D GEM model of lung adenocarcinoma, the same was not true in a lung adenocarcinoma model driven by expression of a mutationally-activated form of the EGF receptor." (PMID 31452510, 2019). "Notably, simultaneous KrasG12D expression and Nkx2-1 inactivation induces mucinous-type lung adenocarcinomas, whereas KrasG12D expression alone induces only non-mucinous type lung adenoma/adenocarcinomas." (PMID 25961920, 2016).
lung adenocarcinoma (continued). "Interestingly, NKX2-1 (more commonly known as Thyroid Transcription Factor-1 or TTF-1), a common immunohistochemical marker of lung adenocarcinomas, was among the top 20 classification markers and had higher expression levels in lung SCC compared to HNSCC cancers." (PMID 23497426, 2013). "In lung adenocarcinomas, NKX2-AS1 and NKX2-1 were highly expressed, but NKX2-AS1 did not regulate the expression of NKX2-1 or nearby genes." (PMID 32083005, 2020). "In lung adenocarcinoma, absence of the pulmonary lineage specifier NKX2-1/TTF1 correlates with non-pulmonary cellular identities and poor prognosis compared with NKX2-1-positive tumors." (PMID 30475207, 2018).
thyroid cancer (30 papers, 2010 to 2026). "TTF-1, a nuclear protein encoded by the NKX2-1 gene, is highly specific for lung and thyroid carcinomas, while Napsin A, an aspartic protease, is specific for pulmonary adenocarcinomas." (PMID 40740944, 2025). "Of note, CREB, the main transcription factor that binds to CRE elements, and NKX2-1 have fundamental roles in thyroid differentiation, and their loss is a hallmark of thyroid cancer progression." (PMID 33176626, 2021). "This study aimed to examine the effects of NKX2-1 re-expression on dedifferentiated thyroid cancer cell death and explore the underlying mechanisms." (PMID 34748583, 2021). "The results reveal that NKX2-1 expression levels were significantly lower in LUSC but significantly higher in thyroid carcinoma (THCA)." (PMID 38708353, 2024). "This study provides a new transgenic model for independent investigation of BRAFV600E-induced lung and thyroid cancer using the shared lineage-defining transcription factor Nkx2-1 as Cre driver." (PMID 37534159, 2023). "These included ABL1 and the master regulator NKX2-1 in thyroid cancer, ERBB3 in liver cancer and AKT3 in colorectal adenocarcinoma." (PMID 35725412, 2022). "One limitation of the present study is that we examined only two papillary thyroid carcinoma derived cell lines and were unable to assess the effects of NKX2-1 overexpression in other thyroid cancer cells, such as PDTC or anaplastic thyroid carcinoma." (PMID 34748583, 2021). "Accordingly, exploring factors that effectively induce NKX2-1 re-expression would lead to novel approaches for treating dedifferentiated thyroid cancer." (PMID 34748583, 2021). "We have previously reported that both TG and TPO mRNA and protein are re-expressed in dedifferentiated thyroid cancer cells (NKX2-1−/PAX8+) infected with adenoviral vectors containing Nkx2-1 (AdNKX2-1), which induces radioiodide organification and retention." (PMID 34748583, 2021). "We have previously reported that NKX2-1 re-expression in dedifferentiated thyroid cancer cells is induced by histone deacetylase (HDAC) inhibitors." (PMID 34748583, 2021). "The observations in the NKX2-1-re-expressed thyroid cancer cells suggested that NKX2-1 suppresses thyroid cancer cell progression, as well as maintains the functions of normal thyroid follicular cells." (PMID 34748583, 2021). "Immunohistochemical analysis showed that NKX2-1 expression decreases in thyroid cancer, corresponding to the progressive thyroid tumor dedifferentiation." (PMID 34748583, 2021). "RGS4 expression suppression partially inhibited cell death, apoptosis, and necrosis after NKX2-1 re-expression in dedifferentiated thyroid carcinoma cells." (PMID 34748583, 2021). "Genes related to thyroid cancer development are involved in DNA repair, ATM (ataxia–telangiectasia mutated) signaling, RET (receptor tyrosine kinase) signaling, and the regulation of thyroid activity (FOXE1, NKX2-1, TSHR)." (PMID 40361383, 2025). "Similarly, while we demonstrated the TG and TPO re-expression in dedifferentiated thyroid cancer cells by Nkx2-1 transduction, we coincidentally observed cell death." (PMID 34748583, 2021). "In thyroid cancer, NKX2-1 expression decreases in parallel with declined differentiation." (PMID 34748583, 2021). "Thyroid transcription factor 1 (TTF1 NKX2-1) missense mutation has been implicated in thyroid tumorigenesis of familial non-medullary cancer, it is responsible for an increased proliferation rate of tumor cells in a rat tumor model of thyroid cancer." (PMID 29561759, 2018). "To functionally explore this hypothesis we initially investigated the levels of ABI3 and NKX2-1 in 5-aza-dC treated and untreated thyroid carcinoma and melanoma cells lines." (PMID 27036019, 2016).
thyroid cancer (continued). "Nevertheless, our data may also be of interest for analyses and assessment of NKX2-1 in lung and thyroid cancer." (PMID 23637834, 2013). "However, the molecular pathways and mechanisms connecting NKX2-1 to thyroid cancer phenotypes are largely unknown." (PMID 34748583, 2021). "Furthermore, NKX2-1 expression decreases in dedifferentiated thyroid carcinoma cells." (PMID 34748583, 2021). "DICER1, NKX2-1, PAX8, and CREB expression levels were evaluated by gene and protein expression in vitro and by interrogation of The Cancer Genome Atlas (TCGA) thyroid cancer data." (PMID 33176626, 2021). "We studied the expression of NKX2-1, PAX8, and DICER1 in the three thyroid cancer cell lines concurrently." (PMID 33176626, 2021). "As cell differentiation is disrupted along thyroid cancer progression and DICER1 is downregulated in thyroid cancer, we next examined the possible transcriptional regulation of DICER1 by NKX2-1 by assessing the functionality of NKX2-1 over the DICER1 promoter." (PMID 33176626, 2021). "Several studies have reported the impaired expression of thyroid transcription factors such as NKX2-1 and PAX8 in thyroid carcinomas, suggesting that their deregulation is pivotal for the initiation and progression of thyroid neoplasms." (PMID 33176626, 2021). "In conclusion, forced NKX2-1 expression using adenoviral vectors induced cell death in dedifferentiated thyroid cancer cells not expressing NKX2-1." (PMID 34748583, 2021). "We have previously reported that AdNKX2-1 infection induced TG promoter activation in thyroid cancer cells not expressing NKX2-1, but not in MDCK cells." (PMID 34748583, 2021). "The existence of a positive feedback loop between NKX2-1 and DICER1 might have important implications in thyroid cancer, as is supported by the positive correlation between both proteins in a series of patient samples analyzed here." (PMID 33176626, 2021). "This study demonstrated that NKX2-1 transduction into dedifferentiated thyroid carcinoma cells that do not express NKX2-1 using an adenoviral vector induces cell death." (PMID 34748583, 2021). "We demonstrated that NKX2-1 expression using adenoviral vectors led to NKX2-1-non-expressing thyroid carcinoma cell death." (PMID 34748583, 2021). "In addition, cell death was not induced in MDCK kidney cells expressing PAX8, but not NKX2-1, whose expression pattern is identical to that of the thyroid cancer cells used in this study." (PMID 34748583, 2021). "Therefore, this study aimed to examine the effects of NKX2-1 re-expression on cell death in dedifferentiated thyroid cancer cells lacking NKX2-1 expression." (PMID 34748583, 2021). "As these thyroid cancer cells expressed PAX8 but not NKX2-1, cell death was seemingly due to the effects induced by NKX2-1 re-expression." (PMID 34748583, 2021).